TLR4 (toll like receptor 4)
Diseases named in the same sentence as TLR4 in open-access papers (continued):
Sharing a sentence is not in itself a finding about the gene and the disease.
colorectal cancer (continued). "LPS, “a major component of the outer membrane of Gram-negative bacteria” is among the most potent TLR4 agonists which may affect the response to 5-FU chemotherapy in colorectal carcinoma." (PMID 24250621, 2013). "Thus, recombination of TLR4, MD-2, and CXCR7 may prove to be valuable prognostic markers for predicting the proliferation and metastatic ability of colorectal carcinoma cells." (PMID 22180778, 2011). "However, the function and regulatory mechanisms of CXCR4/CXCR7 and the relationship between TLR4-MD-2 and CXCR4/CXCR7 in colorectal carcinoma is still unknown." (PMID 22180778, 2011). "Moreover, there are statistically significant differences in high expression of single TLR4, MD-2, or CXCR7 molecules, and high expression of both of TLR4/CXCR7, or MD-2/CXCR7 molecules with regard to distant metastasis in patients with colorectal carcinoma (p = 0.009, p = 0.001, resp.)." (PMID 22180778, 2011). "Inhibition of TLR4, MD-2, or CXCR7 may be an effective adjuvant therapy for colorectal carcinoma." (PMID 22180778, 2011). "In addition, the incidence of distant metastasis tended to be higher in patients with colorectal carcinoma with high rather than low expression of TLR4 or MD-2 (p = 0.003, p = 0.027, resp.)." (PMID 22180778, 2011). "In this study, we found that TLR4 positive colorectal cancer cells demonstrated a higher chemotherapy resistance potential than TLR4 negative colorectal cancer cells, which indicated that TLR4 may also serve as a marker of colon cancer stem cells in colon cancer." (PMID 36647071, 2023). "Toll-like receptor 4 (TLR4), which is responsible for recognizing Gram-negative bacterial LPS, is upregulated and overexpressed in patients with IBD or colorectal carcinoma whereas TLR4 normally is expressed at low level in the intestinal mucosa." (PMID 22180778, 2011).
rheumatoid arthritis (169 papers, 2008 to 2026). A chronic, systemic autoimmune disorder characterized by inflammation in the synovial membranes and articular surfaces. "It has been demonstrated that hyperactivation of TLR4 triggers the production of various inflammatory factors that are associated with the development of a variety of diseases, such as rheumatoid arthritis and cardiovascular diseases." (PMID 38983788, 2024). "In rheumatoid arthritis, osteoclast formation is induced by NETs through toll-like receptor 4 signaling and NET-associated proteins such as histones and NE." (PMID 40066121, 2024). "TLR4, the main host-cellular-receptor for endotoxin recognition, is implicated in the pathogenesis in Rheumatoid Arthritis, cardiovascular disease, and type II diabetes." (PMID 35677024, 2022). "In this regard, several studies have examined the associations with TLR4+896A/G (Asp299Gly/rs4986790) and +1196C/T (Thr399Ile/rs4986791) polymorphisms and autoimmune disease course like rheumatoid arthritis and chronic psoriasis." (PMID 33204706, 2020). "The distinct roles of TLR2 and TLR4 in immunomodulation was further emphasized by findings that TLR2-deficient mice experienced increased joint inflammation in preclinical rheumatoid arthritis (RA) models, while TLR4-deficient mice were more resistant." (PMID 21435210, 2011). "Advance research has reported that excessive Prevotella copri could over-activate toll-like receptor 4, up-regulate inflammatory pathways such as c-Jun N-terminal kinase and nuclear factor-κB to increased rheumatoid arthritis risk." (PMID 33546299, 2021). "In addition to TLR3, which was shown to be involved in the recognition of self-RNAs released from necrotic synovial fluid cells in rheumatoid arthritis patients, TLR4 has been implicated in the recognition of various DAMPs in different autoimmune processes." (PMID 29416536, 2018). "SNPs within the TLR4 gene have been linked to an elevated risk of various inflammatory disorders, including rheumatoid arthritis (RA), ulcerative colitis, and CD." (PMID 38003572, 2023). "For example, berberine alleviates acute lung injury by inhibiting the TLR4/NF-κB pathway, while tetramethylpyrazine derived from Ligusticum chuanxiong Hort granules mitigate joint destruction in rheumatoid arthritis by suppressing MAPK signaling." (PMID 40529488, 2025). "Recent reports from our laboratory have revealed promising therapeutic implications of TLR4 signaling blockade in experimental models of rheumatoid arthritis using TAK-242." (PMID 40948754, 2025). "Pharmacological ablation of TLR4 signaling is shown to alleviate pathological outcomes in animal models of rheumatoid arthritis." (PMID 40948754, 2025). "M2 macrophages in the rheumatoid arthritis (RA) synovial microenvironment are particularly susceptible to ferroptosis, where the HMGB1/ Toll-like Receptor 4 (TLR4)/STAT3 axis plays a pivotal role in exacerbating synovial inflammation." (PMID 41326356, 2025). "In OA models, U50,488H attenuates M1 macrophage polarization through NF-κB inhibition, whereas the non-selective antagonist naltrexone exerts similar anti-inflammatory effects by targeting the Toll-like receptor 4 (TLR4)/NF-κB axis in rheumatoid arthritis." (PMID 41573725, 2025). "Sustained activation or dysregulation of TLR-4 contributes to inflammatory and autoimmune diseases such as Crohn’s Disease, atherosclerosis, rheumatoid arthritis, type 1 diabetes, and other neurodegenerative diseases." (PMID 39329114, 2024). "miR-515-5p modulates fibroblast-like synoviocytes in rheumatoid arthritis by enhancing cell proliferation and diminishing apoptosis via the TLR4/JNK pathway and the WISP1 gene." (PMID 39530095, 2024). "The anti-TLR-4 directed actions of carvacrol have been further demonstrated in various tissues such as stimulated cardiomyocytes, rheumatoid-arthritis-induced fibroblast-like synoviocytes, vascular endothelial cells, and brain neuronal cells." (PMID 36830689, 2023).
rheumatoid arthritis (continued). "The Asp299Gly polymorphism of TLR4 has been implicated in the pathogenesis of systemic lupus erythematosus (SLE) and rheumatoid arthritis (RA)." (PMID 37998389, 2023). "miR-548a-3p has been found to inhibit the proliferation and activation of macrophage-like (pTHP-1) cells by regulating the TLR4/NF-κB signaling pathway in rheumatoid arthritis." (PMID 37254147, 2023). "The Toll-like receptor-4 (TLR-4) signaling pathway plays a crucial role in inflammation including rheumatoid arthritis." (PMID 35807562, 2022). "In rheumatoid arthritis patients, the endogenous TLR4 agonist HMGB1 was detected in increased levels in the serum and synovial tissues, providing another link to TLR4 signaling in inflammatory disorders." (PMID 36678520, 2022). "The mTOR/AKT/AMPK-LC3-ubiquitin signaling axis takes part in this process that bridges mast cell activation and TLR4 degradation in rheumatoid arthritis." (PMID 35292659, 2022). "TLR’s are involved in T cell independent B cell activation, and increased TLR-4 signaling has been associated with increased pain and symptom severity among women with IC/BPS, and other inflammatory pain conditions, including rheumatoid arthritis." (PMID 35193610, 2022). "In total, we found that D3R on mast cells alleviated inflammation in mouse rheumatoid arthritis through the mTOR/AKT/AMPK-LC3-ubiquitin-TLR4 signaling axis." (PMID 35292659, 2022). "TLR4 inhibition is currently being explored for treatment of Rheumatoid Arthritis with varying success." (PMID 35677024, 2022). "In conclusion, we proved that D3R inhibited mast cell inflammation that alleviated mouse rheumatoid arthritis by promoting TLR4 degradation." (PMID 35292659, 2022). "(C) Wilforlide improves rheumatoid arthritis progression, which inhibits M1 macrophage polarity and blocks Toll-like receptor 4 (TLR4) through activation of the NF-κB p65 pathway." (PMID 36263142, 2022). "In clinical cases, EVs isolated from the plasma of patients with rheumatoid arthritis or secreted from cells subjected to oxidative stress contained oxidized phospholipids that activate Toll-like receptor 4 (TLR4)." (PMID 35204238, 2022). "It has been demonstrated that FnBPs can bind to the FNI module of the FN protein, while the FN protein can activate the TLR-4 and then regulate the signaling pathways in a variety of diseases, such as rheumatoid arthritis and chronic skin fibrosis." (PMID 35859766, 2022). "In patients with rheumatoid arthritis (RA), neutrophil extracellular traps (NETs) induced hyperalgesia by acting on Toll-like receptors (TLR-4 and TLR-9), and the production of NETs was positively correlated with the degree of pain." (PMID 35859655, 2022). "NI-0101 is a humanized monoclonal antibody against TLR4, which was tested in clinical trial phase II against rheumatoid arthritis (NCT03241108)." (PMID 34671606, 2021). "In rheumatoid arthritis, an autoimmune inflammatory disease, another member of the miR-548 family, miR-548a-3p, was significantly down-regulated in serum samples targeting Toll-like receptor 4/nuclear factor kappa B (TLR4/NF-kappaB) signaling pathway." (PMID 34178725, 2021). "In order to identify how the synovial microenvironment impinges on CD4+ T cells pathogenic functions in Rheumatoid Arthritis (RA), Amaral-Silva examined RA patient blood and synovial fluif and identified the presence of a TLR4+ follicular helper T (Tfh) cell-like population." (PMID 34580414, 2021). "Yan et al42 found that lncRNA HIX003209 did not directly bind to TLR2, TLR4 and NF‐κB; however, it promoted TLR4/NF‐κB expression in macrophages through the sponge miR‐6089, which was critical for the development of rheumatoid arthritis." (PMID 33728802, 2021). "Stimulation of TLR2 and TLR4 could enhance the inflammatory response in rheumatoid arthritis (RA), and the expression of TLRs was found to be associated with the incidence of inflammatory bowel disease (IBD) and the pathogenesis of Behcet’s disease." (PMID 35069523, 2021).
rheumatoid arthritis (continued). "IL-29 upregulates synovial-fibroblast TLR4, which enhances synovium inflammation in rheumatoid arthritis (RA)." (PMID 34206009, 2021). "TQ was reported to downregulate pro-inflammatory genes such as IL-1, TNF-α, and toll-like receptors (TLR2, TLR4) and attenuate rheumatoid arthritis via the NFkB pathway." (PMID 32793594, 2020). "The wide spectrum of clinical settings to which TLR4 inhibitors can be applied include autoimmune diseases (rheumatoid arthritis, inflammatory bowel diseases), vascular inflammation, neuroinflammations, and neurodegenerative diseases." (PMID 32765484, 2020). "It was observed that ESP-B4 helps diminish inflammation by reducing the release of inflammatory factors and cytokines from the Toll-like receptor 4 (TLR4) signaling pathway to treat rheumatoid arthritis." (PMID 32698308, 2020). "The high mobility group box protein 1 DAMP, released by damaged synovial cells in patients with rheumatoid arthritis has been shown to activate TLR4." (PMID 29422061, 2018). "Similar results were obtained in IFNγ and TLR4 activated mouse macrophages, TLR4 stimulated splenocytes, TLR4 activated PBMCs from healthy donors and patients with rheumatoid arthritis, as well as, TLR7 engaged macrophages." (PMID 30546359, 2018). "For instance, the inhibition of TLR4 in rheumatoid arthritis animal models, characterized by local and systemic reduction in bone mineral density, suppressed the severity of the disease." (PMID 29867550, 2018). "The aim of the study was to determine whether polymorphisms in toll-like receptor 4 (TLR4) confer susceptibility to rheumatoid arthritis (RA) and juvenile idiopathic arthritis (JIA) in a central south Chinese Han population." (PMID 28222760, 2017). "Toll-like receptor 4 was proposed to play an important role in various autoimmune diseases, such as rheumatoid arthritis, systemic lupus erythematosus, and multiple sclerosis." (PMID 28446897, 2017). "For example, the expression of TLR4 was increased in rheumatoid arthritis, systemic lupus erythematosus, and multiple sclerosis." (PMID 28446897, 2017). "Both TLR2 and TLR4 are highly expressed in varying levels of osteoarthritic chondrocytes, as well as in synovial tissue of rheumatoid arthritis patients." (PMID 24457003, 2014). "In another report, ICs suppressed the TLR4-mediated response of DCs in rheumatoid arthritis patients through FcγRIIb." (PMID 23744091, 2013). "Furthermore, LINC01197 can alleviate rheumatoid arthritis, a common systemic autoimmune disease, by sponging miR-150 to promote TLR4/NF-κB inactivation." (PMID 39334466, 2024). "This study delved into the intricate landscape of rheumatoid arthritis and provided exclusive insights into the role of miRNA128a, the TLR4 signaling pathway and adenosine in RA pathogenesis by modulating FADD tissue expression and FADD microvesicular shedding in synovial fluid." (PMID 38919260, 2024). "In addition, miR-548a-3p is markedly downregulated in rheumatoid arthritis patients and modulates inflammation through the TLR4/NF-κB signaling pathway." (PMID 39530095, 2024). "Moreover, WMP (0.5 g/kg, 2 g/kg) restricted arthritis and immune organ indices in CIA rats with type II collagen-induced rheumatoid arthritis by blocking TLR4-NF-κB inflammatory pathway activation." (PMID 38218891, 2024). "Moreover, for TH22/17-associated autoimmune conditions including rheumatoid arthritis, TLR2, TLR4, and TLR5 modulation holds potential for managing these disorders." (PMID 37760825, 2023). "In addition, TLR4 is closely related to changes in bone metabolism in rheumatoid arthritis, osteoarthritis, and other diseases." (PMID 37252680, 2023). "For HLBW and SBW, TGFB3 and TLR4 were enriched to the pathway of rheumatoid arthritis." (PMID 38200769, 2023). "Furthermore, inhibitors of TLR4 improved symptoms of patients with rheumatoid arthritis in a preliminary phase 1 trial." (PMID 35292659, 2022).
rheumatoid arthritis (continued). "Our findings suggest that TLR4/TNF-α might be a potential target to suppress bone loss associated with inflammatory bone diseases, including periodontitis, rheumatoid arthritis, and osteoporosis." (PMID 33765924, 2021). "TLR4's SNPs might alter disease severity in rheumatoid arthritis by modifying the TLR4 function and/or its gene expression." (PMID 33204706, 2020). "Also, a recent study reported that TQ exerts anti-inflammatory effects by reduction of TNF-α, TLR-2, TLR-4, and Interleukin-1 in rheumatoid arthritis." (PMID 32793594, 2020). "NI-0101 is the first monoclonal anti-TLR4 antibody entering clinical development, which declared that could block rheumatoid arthritis (RA) synovial fluids-induced pro-inflammatory cytokine production." (PMID 33597886, 2020). "An increase in expression of TLR2 and TLR4 has also been observed in the synovial membrane collected from patients with other SpAs, including with PsA and undifferentiated SpA, compared to patients with rheumatoid arthritis (RA) and osteoarthritis (OA)." (PMID 29283375, 2017). "Alternatively, strategies to block the functional activity of TLR4-expressing effector cells may also be helpful in treating rheumatoid arthritis." (PMID 23036692, 2012). "Furthermore, an inhibitor of TLR4 has reduced symptoms in patients with moderate to severe rheumatoid arthritis in a preliminary phase 1 trial." (PMID 21858160, 2011). "TLR4 has been shown to up-regulate FcγR expression in experimental immune complex arthritis; inhibition of TLR4 resulted in attenuation of in vivo cytokine release in models of glomerulonephritis and rheumatoid arthritis." (PMID 19503602, 2009). "Chaperonin 10 exhibits anti-inflammatory effects by inhibiting TLR4 activation, as demonstrated in clinical studies in rheumatoid arthritis (RA)." (PMID 41156105, 2025). "TLR4 and CD14 SNPs may qualitatively and/or quantitatively alter the expression, affecting the susceptibility and severity of systemic lupus erythematosus (SLE) and rheumatoid arthritis (RA)." (PMID 37176151, 2023). "We tested whether the TLR4 inhibitor TAK-242 had potential as a remedy for rheumatoid arthritis." (PMID 31973752, 2020). "Based on the drug repositioning concept, TAK-242, which is used for the treatment of TLR4-mediated inflammatory diseases, shows potential for cost-effective development as a remedy for rheumatoid arthritis or to control the progression of RA." (PMID 31973752, 2020). "Starting with the antibodies, NI-0101 (Novimmune, Plan-les-Ouates, Switzerland) is the first anti-TLR4 antibody designed for rheumatoid arthritis (RA)." (PMID 32605223, 2020). "Toll-like receptor 4 (TLR-4) is the key receptor involved in lipopolysaccharide (LPS) endotoxin recognition and activation of the innate immune system, and has also been implicated in the pathogenesis of autoimmune conditions such as systemic lupus erythematosus (SLE) and rheumatoid arthritis." (PMID 30390640, 2018). "It is becoming clear that TLRs are involved in systemic autoimmune disorders, because it was recently demonstrated TLR2 and TLR4 are involved in rheumatoid arthritis (RA) and TLR9 in systemic lupus erythematosus." (PMID 18234118, 2008). "Toll-like receptor 4 (TLR4), which is expressed in chondrocytes, osteoblasts, and synoviocytes, assumes greater significance in the pathophysiology of rheumatoid arthritis." (PMID 40948754, 2025). "For instance, TLR4 plays a role in rheumatoid arthritis (RA) and antiphospholipid syndrome (APS)." (PMID 40700292, 2025). "TAK-242, a specific TLR4 inhibitor, has been used for the treatment of rheumatoid arthritis (RA)." (PMID 37020586, 2023). "It was reported that hsa-miR-515-5p regulated WISP1 expression, inhibited the TLR4/JNK signaling pathway, and reduced apoptosis in fibroblast-like synoviocytes (RAFLS) of rheumatoid arthritis." (PMID 37313407, 2023).